TPH1 (tryptophan hydroxylase 1)
Description:
Oxidizes L-tryptophan to 5-hydroxy-l-tryptophan in the rate-determining step of serotonin biosynthesis.
Synonyms: TPRH; TRPH; formerly TPH
Tractability: Small molecule: an approved drug acts on it; a structure with a bound ligand is known; a high-quality ligand is known; it has a binding pocket of medium quality; it belongs to a druggable protein family. PROTAC: UniProt records ubiquitination sites on it; a small molecule that binds it is known.
Target class: Enzyme; Oxidoreductase
Gene: Protein-coding gene on chromosome 11 (18,017,555 to 18,046,269, reverse strand). Ensembl gene ENSG00000129167.
Subcellular location (Human Protein Atlas): Cytosol
Pathways (Reactome):
Metabolism: Serotonin and melatonin biosynthesis
Signal Transduction: NGF-stimulated transcription
Gene Ontology:
Molecular function: protein binding; tryptophan 5-monooxygenase activity; iron ion binding; monooxygenase activity; oxidoreductase activity, acting on paired donors, with incorporation or reduction of molecular oxygen, reduced pteridine as one donor, and incorporation of one atom of oxygen
Biological process: platelet degranulation; regulation of hemostasis; serotonin biosynthetic process; aromatic amino acid metabolic process
Cellular component: cytosol; neuron projection; cytoplasm
Genetic constraint (gnomAD): Loss-of-function variants: 34 observed, 49.15 expected, observed/expected ratio (o/e) 0.69, 90% interval 0.52 to 0.92. The upper end of that interval is the gene's LOEUF score, 0.92, which puts it in group 3 of 6, group 1 being the genes least tolerant of losing a copy. Missense variants: 474 observed, 542.75 expected, observed/expected ratio (o/e) 0.87, 90% interval 0.81 to 0.94. Synonymous variants: 160 observed, 192.56 expected, observed/expected ratio (o/e) 0.83, 90% interval 0.73 to 0.95.
Homologues: Orthologues: chimpanzee TPH1 (99% identical), macaque TPH1 (99% identical), dog TPH1 (98% identical), pig TPH1 (97% identical), mouse Tph1 (90% identical), guinea pig TPH1 (89% identical), zebrafish tph1a (78% identical), zebrafish tph1b (75% identical), Drosophila melanogaster Trhn (59% identical), Caenorhabditis elegans tph-1 (50% identical). Paralogues in human: TPH2 (72% identical), PAH (54% identical), TH (49% identical).
Diseases named in the same sentence as TPH1 in open-access papers:
TPH1 is named in the same sentence as 147 diseases in open-access papers, as found by Europe PMC text mining. Sharing a sentence is not in itself a finding about the gene and the disease. The quoted sentences say what the papers report.
depression (52 papers, 2011 to 2026). "If TPH1 mutation occurs, it is closely related to human neuropsychiatric diseases such as personality disorder, schizophrenia, emotion regulation, depression, and even intelligence quotient." (PMID 39309474, 2024). "The next important enzymes associated with depression are tryptophan hydroxylase 1 and 2 (TPH1, TPH2)." (PMID 32406039, 2020). "The T/T genotype of c.‐1668T>A—TPH1 (rs623580) was negatively correlated with depression, while genotype A/A and allele A of the same SNP were positively correlated with the disease." (PMID 29314569, 2018). "The association between depression and haplotypes of the studied polymorphisms of the TPH1 or TPH2 genes was also assessed." (PMID 29314569, 2018). "The TA, AC and AA haplotypes of c.‐1668T>A—TPH1 (rs623580) and c.803+221C>A—TPH1 (rs1800532) were responsible for an increased risk of depression development, while the TC haplotype of the same polymorphism combination decreased this risk." (PMID 29314569, 2018). "An increase by seven times of the risk of depression was confirmed for the A/A‐C/A combined genotypes of c.‐1668T>A—TPH1 (rs623580) and c.‐1449C>A—TPH2 (rs7963803) (P = 0.011)." (PMID 29314569, 2018). "The role of Tryptophan Hydroxylase 1 (TPH1) gene is implicated in various psychiatric disorders, including depression." (PMID 27672527, 2016). "Our findings suggest that AA genotype (50%) and the frequency of A allele (70.28%) in TPH1 A779C was found associated with major depressive disorders (p ≤ 0.0001)." (PMID 27672527, 2016). "Although genetics of depressive disorders appears to be understudied and least explored in India, our preliminary study shows that TPH1 A779C was found associated with MDD in Kashmiri population." (PMID 27672527, 2016). "As the association of TPH1 gene in depressive disorders in some studies has shown positive association and it was not possible to study all the variants of TPH 1 gene, due to financial and time restraints, TPH1 A779C variant was selected." (PMID 27672527, 2016). "In the present study, we use a case-control study design to investigate the association of TPH1 A779C gene polymorphism in depressive disorders in Kashmiri (Indian) population." (PMID 27672527, 2016). "A study of SNPs in TPH1 found associations with comorbid depression and anxiety in a population-based sample of postpartum Taiwanese women." (PMID 27617302, 2015). "Genetic studies have reported an association between TPH1 and depression, or the responsiveness of depression to antidepressive medication." (PMID 25540092, 2014). "TPH1 is associated with depression or the responsiveness of depression to antidepressive medication, by a considerable number of genetic studies." (PMID 25540092, 2014). "By contrast, in a study where TPH1 CC-genotype was found to occur more commonly among patients with major depression, the same genotype was associated both with the severity of the disease and with lower probability of achieving remission." (PMID 23597148, 2013). "Two groups analyzed TPH1 single-nucleotide polymorphism (SNP) and haplotype differences between participants with depression and control participants." (PMID 23680237, 2013). "Given the clinical state of major depression and the underlying risk traits, it seems that despite the achievement of remission the impact of depression risk traits differs depending on the TPH1 genotype." (PMID 23597148, 2013). "In major depression, one of the candidate genes possibly affecting the risk and severity of symptoms has been found to be tryptophan hydroxylase (TPH1)." (PMID 23597148, 2013). "Associations between TPH1 genotype and temperament dimensions were studied in patients with major depressive disorder and linear changes were found at both baseline and endpoint." (PMID 23597148, 2013). "TPH1 A218C polymorphism has been suggested to have an impact on depressive disorders and suicidal behavior." (PMID 23597148, 2013).
depression (continued). "Despite the peripheral localization of this enzyme, some single-nucleotide polymorphisms, both in the coding and in the non-coding regions of the human TPH1 gene, have been associated with an increased susceptibility to depression, post-traumatic stress disorders, and alcohol abuse." (PMID 35563331, 2022). "Our results confirmed that 5-HT and TPH1/2 dysfunction were associated with depression." (PMID 28968985, 2017). "Different studies have shown an association of TPH1 gene variants with depressive disorders." (PMID 27672527, 2016). "However, all those studies showing a positive association of TPH1 A779C gene with depressive disorders were done in western countries." (PMID 27672527, 2016). "Subsequently, endogenous depression may be caused by TPH1 dysfunction combined with compensatory TPH2 activation." (PMID 25540092, 2014). "Peripheral 5-HTP cells provide an endogenous substrate for L-aromatic amino acid decarboxylase in 5-HT cells, and it is possible that hypofunctional 5-HTP cells (reflecting TPH1 dysfunction) in the periphery lead to deficient brain 5-HT levels, and may be a factor for depression." (PMID 25540092, 2014). "In a model of depression induced by chronic unpredictable stress, the expression of tryptophan hydroxylase 1 (TPH1)—the enzyme crucial for 5-HT synthesis—was markedly downregulated in intestinal EC cells, resulting in a decreased colonic 5-HT concentration." (PMID 41305570, 2025). "The aim of this study was to investigate the association between the genetic type and alleles for the TPH1, TPH2, SLC6A4, HTR1A, HTR2A, and BDNF genes in Korean suicide attempters with major depressive disorder (suicide attempters) and a control group." (PMID 41300755, 2025). "Cereulide arouses depression in different animal species by inhibiting the production of tryptophan hydroxylase 1 and 2 (TPH-1 and TPH-2), key enzymes for the precursor of serotonin (5-HT) synthesis, which controls depression behavior." (PMID 36832907, 2023). "Some researchers have implicated a large number of gene-related depression, including CACNA1E, BDNF, CRHR1, GSK3β, TPH1, and so on, see those in the systematic review." (PMID 36937715, 2023). "Some studies have implicated a large number of genes associated with depression, including HTR2A, CACNA1C, BDNF, CRHR1, GSK3β, TPH1, among others, as detailed in a systematic review." (PMID 38075264, 2023). "Rats exposed to SPS also exhibit reductions in the mRNA expression of TPH-1 in the Hipp, which leads to anxiety- and depression-like behaviors." (PMID 32143600, 2020). "We also noticed a link between the CA haplotype of c.804‐7C>A—TPH1 (rs1799913) and c.‐1668T>A—TPH1 (rs623580), and the increased rate of depression." (PMID 29314569, 2018). "The objective of our study was to confirm the association between the presence of polymorphic variants of TPH1 and TPH2 genes, and the development of depressive disorders." (PMID 29314569, 2018). "Two isoforms of the gene encoding tryptophan hydroxylase (TPH1 and TPH2), a major biosynthetic enzyme for serotonin, have been linked to depression." (PMID 27617302, 2015). "Our result of microarray analysis and RT-PCR result showed that the expression of Tph1 was increased after acupuncture treatment which indicated that acupuncture had a potential effect on poststroke depression by promoting the level of 5-HT in brain." (PMID 25861363, 2015). "Potentially, all types of depression can be expressed through combinations of these key enzymes using a matrix with peripheral (TPH1, TDO, IDO) and central (TPH2, KMO) determinants." (PMID 25540092, 2014). "Earlier studies, including one meta-analysis, have reported contradictory results on the relationship between TPH1 genotype and treatment response in major depression." (PMID 23597148, 2013).
depression (continued). "Tryptophan 5-hydroxylase 1 (TPH1) is the rate-limiting enzyme in 5-HT biosynthesis and alterations in this enzyme have been implicated in depression, suicide attempts, deliberate self-harm and the antidepressant-treatment response." (PMID 23847536, 2013). "Furthermore, in mouse models of reserpine-induced depression, scopolamine can reverse the decrease in TPH1 levels in the hippocampus and prefrontal cortex." (PMID 36037970, 2022). "Indeed, studies also correlate the expression of TPH1 enzyme with depression and responses to antidepressant medication." (PMID 35955633, 2022). "Another important function of VD interferes with the synthesis of serotonin by the expression of serotonin‐synthesizing gene tryptophan hydroxylase 1 and tryptophan hydroxylase 2, and VD may thus prevent depression by maintaining normal serotonin levels." (PMID 32945627, 2020). "In summary, the c.804‐7C>A, c.‐1668T>A, c.803+221C>A and c.‐173A>T polymorphisms of the TPH1 gene and the c.‐1449C>A, c.‐844G>T polymorphism of the TPH2 gene may be associated with depression in the Polish population." (PMID 29314569, 2018). "Additionally, the increased risk of DD occurrence was associated with the T/T‐C/A combined genotype of c.‐173A>T—TPH1 and c.‐1449C>A—TPH2 (rs10488682 versus rs7963803); however, the T/A‐C/C genotype decreased the risk depression occurrence." (PMID 29314569, 2018). "However, the T/T homozygote of c.‐1668T>A—TPH1, the G/T heterozygote and T allele of c.‐844G>T—TPH2, and the C/C homozygote and C allele of c.‐1449C>A—TPH2 decreased the risk of development of depressive disorders." (PMID 29314569, 2018). "Etiological classification of depression expressed by peripheral (TPH1, TDO, IDO) and central (TPH2, KMO) enzymes of tryptophan metabolism may enable depression to be viewed as a clear box, with the inner components available for inspection and treatment." (PMID 25540092, 2014). "It is possible that hypofunctional 5-HTP cells (reflecting TPH1 dysfunction) in the periphery, leading to deficient 5-HTP, low 5-HT, and concomitant compensatory TPH2 activation in the brain, may cause endogenous depression." (PMID 25540092, 2014). "According to the present study, TPH1 A218C genotype differentiates between temperament profiles and changes therein in acute major depression, which is supported by genotype-specific differences found in HA and NS scores at baseline and endpoint during antidepressive treatment." (PMID 23597148, 2013). "However, the relationship between temperament and TPH1 genotype in major depression is poorly understood, as only one study has been published so far." (PMID 23597148, 2013). "Several studies, including our earlier study, report negative outcomes concerning the association between TPH1 genotype, depression and its treatment response." (PMID 23597148, 2013). "We investigated the interaction between TPH1 A218C polymorphism, SSRI treatment response and temperamental traits assessed by the Temperament and Character Inventory (TCI) in a clinical sample of subjects with major depression." (PMID 23597148, 2013). "So far only one study has been published on temperament traits and TPH1 A218C polymorphism in major depression; it reports a negative result between HA or NS scores and TPH1 genotypes." (PMID 23597148, 2013). "We also used a case-control study design in the same individuals to investigate a possible association with a susceptibility to depression of the SNPs of five other serotoninergic system genes: 5HTR2A (SNP 6313), 5HTR1B (SNP 6296), HTR2C (SNP6318), TPH1 (SNP 1800532), and TPH2 (SNP 7305115)." (PMID 22619623, 2012). "For example, six SNPs in the tryptophan hydroxylase gene (TPH1, TPH2) have been studied to verify the association between polymorphisms in the TPH and the development of depression, and the tryptophan hydroxylase pathway is implicated in the pathogenesis of depression." (PMID 37581520, 2024).
depression (continued). "In animal models of stress and depression, supplementation with Bifidobacterium and Lactobacillus appeared to have an effect on colonic serotonin in mice, and possibly tryptophan availability, since it increased colonic TPH1 and 5-HTP levels, previously decreased by CUMS." (PMID 35216133, 2022). "Polymorphism of A218C TPH1 gene know to be linked with different disorder like Borderline personality disorder (BPD) in United States, suicidal behavior and anger-related personality behaviors, schizophrenia, bipolar disorder in Taiwan, Caucasian population and depression in Finland." (PMID 34411117, 2021). "However, no study has investigated TPH1 A779C gene polymorphism in depressive disorders in a distressed society like Kashmir (India)." (PMID 27672527, 2016). "The present study investigated the effects of the chronic administration of venlafaxine on the expression and methylation status of Katl, Tph1/2, Ido1, Kmo and Kynu in the brain and blood of rats exposed to the CMS model of depression." (PMID 32406039, 2020). "Down-regulation of the tph1 gene in the fetal brain indicates an imbalance of the melatonin system, which may be involved in the sleep disturbances and circadian rhythm disorganization that usually appear in patients with psychiatric conditions such as depression, autism and Alzheimer’s disease." (PMID 28650979, 2017). "Trp, a neurotransmitter precursor, is known to accelerate depression, which led us to hypothesize that MGO-induced depression in mice may be mediated by modulating the levels of Trp and related factors such as 5-HTP, 5-HT, TPH1, and TPH2." (PMID 39574138, 2024). "The described etiological classification expressed by peripheral (TPH1, TDO, IDO) and central (TPH2, KMO) enzymes allows depression to be viewed as a clear box with the inner components, or logic, available for appropriate individualized inspection and treatment." (PMID 25540092, 2014). "Among these, MAOA, COMT, TPH1, and TPH2 have been reported to be associated with depression, but a recent genome-wide association study found no significant genome-wide association, and the best candidates did not involve these pathways." (PMID 21827647, 2011). "Although the underlying mechanism of the gender difference was not clear, this study suggested that the relation between TPH1 rs623580 and depressive disorder might be different between women and men." (PMID 32726303, 2020). "The C/A‐C/A and A/A‐C/A combined genotypes of the c.803+221C>A—TPH1 and c.‐1449C>A—TPH2 (rs1800532 versus rs7963803) may lead to a development of depression, and the C/A‐C/C combined genotype of the same SNPs combination reduce the risk of developing the disease." (PMID 29314569, 2018). "Treatment options from the etiological classification of depression may include gene therapy to rescue intestinal 5-HTP cells or enhance peripheral 5-HTP production and thereby compensate for TPH1 dysfunction, psychotherapy for TDO activation, and anti-inflammatory drugs for IDO activation." (PMID 25540092, 2014). "In multivariate analysis of covariance (MANCOVA) TPH1 genotype was used as a factor and MADRS scores as a covariate, since depressive symptoms have been found to modify temperamental traits and, on the other hand, temperament has an impact on recovery from depression." (PMID 23597148, 2013). "In the present study, 113 women with diagnosed mild or moderate depression (patients) and 219 women without depression (healthy controls) were genotyped for polymorphisms in six serotonergic candidate genes: HTR2A, HTR1B, HTR2C, TPH1, TPH2, and MAO-A." (PMID 22619623, 2012).